ZNF197 (zinc finger protein 197)
Description:
May be involved in transcriptional regulation.
Synonyms: ZKSCAN9; ZNF166; P18; D3S1363E; ZSCAN41; VHLaK
Tractability: PROTAC: ubiquitination databases record sites on it.
Gene: Protein-coding gene on chromosome 3 (44,584,888 to 44,648,471, forward strand). Ensembl gene ENSG00000186448.
Subcellular location: Nucleus
Subcellular location (Human Protein Atlas): Nucleoplasm
Pathways (Reactome):
Gene expression (Transcription): Generic Transcription Pathway
Gene Ontology:
Molecular function: transcription cis-regulatory region binding; sequence-specific double-stranded DNA binding
Biological process: regulation of transcription by RNA polymerase II; regulation of DNA-templated transcription; regulation of gene expression
Cellular component: nucleus
Genetic constraint (gnomAD): Loss-of-function variants: 17 observed, 31.11 expected, observed/expected ratio (o/e) 0.55, 90% interval 0.37 to 0.82. The upper end of that interval is the gene's LOEUF score, 0.82, which puts it in group 3 of 6, group 1 being the genes least tolerant of losing a copy. Missense variants: 1,090 observed, 1,284.5 expected, observed/expected ratio (o/e) 0.85, 90% interval 0.81 to 0.89. Synonymous variants: 415 observed, 444.23 expected, observed/expected ratio (o/e) 0.93, 90% interval 0.86 to 1.01.
Homologues: Orthologues: chimpanzee ZNF197 (99% identical), macaque ZNF197 (98% identical), pig ZNF197 (93% identical), rabbit ZNF197 (85% identical). Paralogues in human: ZNF585B (32% identical), ZNF585A (31% identical), ZNF658 (31% identical), ZNF33B (30% identical), ZNF41 (29% identical), ZFP28 (29% identical), ZNF470 (29% identical), ZNF605 (29% identical), ZNF484 (28% identical), ZNF568 (27% identical), ZNF226 (27% identical), ZNF28 (27% identical), and 164 more.
Diseases named in the same sentence as ZNF197 in open-access papers:
ZNF197 is named in the same sentence as 3 diseases in open-access papers, as found by Europe PMC text mining. Sharing a sentence is not in itself a finding about the gene and the disease. The quoted sentences say what the papers report.
glioma (1 paper, 2013). A benign or malignant brain and spinal cord tumor that arises from glial cells (astrocytes, oligodendrocytes, ependymal cells). "According to the obtained results, ZNF197 gene is a hypoxia regulated gene in glioma cells." (PMID 23826488, 2013).
ZNF197 also shares sentences with these, for which no sentence is quoted: cerebral malaria (1 paper); thyroid papillary carcinomas (1).